CASP1 (caspase 1)
Diseases named in the same sentence as CASP1 in open-access papers (continued):
Sharing a sentence is not in itself a finding about the gene and the disease.
tumor (continued). "Higher levels of CCL5 were also detected in the tumor supernatant of Caspase-1-deficient tumors consistent with an increase in NK cells recruitment and activation." (PMID 33042810, 2020). "IL-1 receptor- or caspase-1-deficient mice showed reduced cancer incidence and tumor numbers compared to wild-type controls." (PMID 32117971, 2020). "To address this finding in our model, we analyzed the tumor immune infiltrate in the mammary gland at days 7 and 14 post-injection in WT, Asc-, and Caspase-1-deficient mice." (PMID 33042810, 2020). "Caspase-1 is downregulated in many cancer types, and its loss enhances tumor formation and promotes cancer development." (PMID 32303673, 2020). "With the exception of NKG2D, few differences were detected between splenic NK cells from WT and Caspase-1-deficient tumor-bearing mice, indicating that the tumor microenvironment directly impacts NK cell phenotype." (PMID 33042810, 2020). "Together, these findings further highlight the critical role of active caspase-1 in mediating metabolic reprogramming of tumor cells, leading to the loss of tumor cells‘ differentiation state." (PMID 33102234, 2020). "As a consequence of gC1qR cleavage by active caspase-1, tumor cells displayed a loss of OXPHOS activity and thereby an imbalanced OXPHOS and glycolysis activity." (PMID 33102234, 2020). "Somewhat similarly, a recent study by Niu and collaborators shows that tumor -associated macrophage differentiation is promoted by caspase-1 cleavage of PPARγ." (PMID 31060333, 2019). "Angiogenesis is a pre-requisite for tumour invasion and inhibition/depletion of caspase-1 has been implicated in the improvement of angiogenesis and blood supply in functional angiogenesis murine models." (PMID 30538296, 2019). "A particularly intriguing NFκB target gene encodes pro-IL-1β, which is processed by caspase-1 or neutrophil protease to the key proinflammatory and tumor-promoting cytokine IL-1β." (PMID 31766169, 2019). "Melanotic tumours have previously been observed in Drosophila larvae in the context of loss of a caspase protein, Drosophila Caspase-1 (dcp), as well as haemopoietic defects upon overproliferation, arising from activation of the JAK/STAT pathway." (PMID 29861494, 2018). "Here, we report that caspase-1 promotes tumor-associated macrophage differentiation by cleaving peroxisome proliferator-activated receptor gamma (PPARγ) at Asp64, thus generating a 41 kDa fragment." (PMID 28974683, 2017). "Implantation of malignant cells admixed with WT BMDMs markedly promoted the tumor growth, whereas caspase-1-deficient BMDMs significantly impaired the tumor growth." (PMID 28974683, 2017). "The reduced tumor growth and metastasis in NLRP3 and caspase-1 deficient mice suggest that inflammasome activity influences tumor development." (PMID 27786298, 2016). "IL-1 receptor- or caspase-1-deficient mice showed reduced cancer incidence and tumor number compared to wild-type." (PMID 27768771, 2016). "NLRP3 deficient mice had reduced tumor growth, which is similar to what we observed in caspase-1 KO mice." (PMID 27786298, 2016). "Compared to WT cells, CD11b cells from tumor tissues of caspase-1 deficient mice secreted significantly less IL-1β." (PMID 27786298, 2016). "The heightened tumor growth in the caspase-1 deficient mice was accompanied with drastically low levels of colonic IL-18." (PMID 25071785, 2014). "As a result, caspase-1 deficient mice show increased colonic epithelial cell proliferation in early stages of tumor formation and reduced apoptosis in advanced tumors." (PMID 23606794, 2013). "Mice with NLRP3 and caspase-1 deficiency subjected to AOM/DSS showed a dramatically increased tumor burden in the colon due to reduced IL-18 levels that altered the production and activation of the tumor suppressors IFN-γ and signal transducer and activator of transcription 1 (STAT1)." (PMID 39684769, 2024).
tumor (continued). "As the inflammasome is a key molecule that induces caspase-1 to undergo pyroptosis, it may be an important node in the association between tumor cells and pyroptosis." (PMID 35883480, 2022). "Notably, we also found that the CASP1 expression was negatively associated with the cancer-associated fibroblast cells and tumor purity." (PMID 35937993, 2022). "Because PPARγ has been reported to be cleaved by caspase-1 in tumor-associated macrophages 45, we tested whether the decreased PPARγ level was owing to cleavage by caspase-1." (PMID 33500734, 2021). "In these mice, ablation of ASC was associated with reduced NF-κB, caspase-1 activation, and enhanced numbers of caspase-3 and -8 positive tumor cells, suggesting a tumor-promoting function for ASC by limiting apoptosis in the gastric epithelium, independently of its pro-inflammatory effects." (PMID 32117971, 2020). "Furthermore, NK cells present in the tumor of Caspase-1-deficient hosts expressed higher levels of NK cell activation markers NKG2D, Granzyme B (GZB), CD69 and CD98." (PMID 33042810, 2020). "We further showed that NK cells from Caspase-1-deficient mice responded better to ex vivo re-stimulations, and NK cell depletion in WT and Caspase-1-deficient mice resulted in similar tumor growth rates, demonstrating the major role of NK cells on tumor growth control." (PMID 33042810, 2020). "Similarly, in a breast cancer model, deficiency of inflammasome components (NLRP3 or caspase-1 knockout) reduced tumor growth and metastasis and was correlated with reduced infiltration of MDSCs within the tumors." (PMID 30631327, 2018). "Knocking down CASP1 in G9A-deficient cell restored capacities of tumor cell invasion and migration." (PMID 28383547, 2017). "The reduced tumor growth and metastasis in caspase-1 deficient mice suggest that blocking inflammasome activity or IL-1R signaling may inhibit tumor growth." (PMID 27786298, 2016). "First, we confirmed that caspase-1 activity was significantly increased in CD11b+ infiltrating cells in a preclinical model, and we directed mechanistic attention toward the tumor-intrinsic factors that regulate myeloid inflammasome signaling that was associated with tumor growth." (PMID 36439171, 2022). "Indeed, in human cancers, caspase-1 is frequently downregulated, and this caspase-1 deficiency may contribute to tumor growth and the progression of tumor cells." (PMID 35883451, 2022). "In order to verify whether the activation of caspase-1 in tumor cells was associated with secretion of mature IL-18, we assessed the link between the expression of aCasp1 in tumor cells and the levels of mature IL-18 released in culture supernatants of CRC explant cultures." (PMID 33430344, 2021). "However, tumor tissues from caspase-1 deficient mice had reduced levels of IL-1β." (PMID 27786298, 2016). "This design enables selective activation in GSH-rich tumor cells, where it depletes intracellular antioxidants, triggers caspase-1/gasdermin-D-dependent pyroptosis, and amplifies ICD." (PMID 41356187, 2026). "MCNR can enhance T-cell infiltration in breast cancer and other tumor tissues, inhibit tumor growth, and achieve real-time monitoring through caspase-1-mediated specific enzyme digestion." (PMID 41556044, 2026). "Comparisons between OSCC tissues and normal oral mucosa consistently reveal elevated expression of NLRP3, caspase-1, and IL-1β, which correlate with advanced tumor stage, lymph node metastasis, and poor clinical prognosis." (PMID 41596738, 2026). "The synergistic photo‐thermoelectric catalysis triggers pyroptosis via reactive oxygen species‐caspase 1‐gasdermin D activation, eliciting robust systemic immunity that effectively eliminates the primary tumor and prevents tumor recurrence." (PMID 40847518, 2026). "Quite strikingly, caspase-1 activity was vastly excluded from the tumor regions, and was most prominently found alongside CD66b positive neutrophilic cells at the tumoral intersection." (PMID 39851539, 2025).
tumor (continued). "As expected, the level of IgA kappa light chain indicated that tumor burden was lower in the sgNPC1 group, and we observed that cleaved caspase-1 level was increased in NPC1-depleted ARP-1 cells from MM-bearing mouse bone marrow." (PMID 41013744, 2025). "In BRAF-mutant CRC, restoring AIM2 expression significantly inhibited tumor growth and induced necrotic cell death in a caspase-1 dependent manner, further underscoring its role as a tumor suppressor." (PMID 40386782, 2025). "Immunostaining for the cleaved (activated) apoptosis marker DCP1 (Death Caspase-1/active caspase-3) revealed a significant increase in apoptotic cells in Ykiact gut tumors compared to both control and Rasact tumor-bearing flies." (PMID 39829769, 2025). "Regarding the MDA-MB-231 cells, the caspase-1 levels were noticeably higher compared with the normal cells, suggesting the inflammatory potential of tumor cells." (PMID 39940603, 2025). "Taken together, these results indicate that the predicted interaction between clindamycin and caspase-1 has the potential to counteract TAM pyroptosis-driven tumor promotion." (PMID 40759978, 2025). "NLRP3 levels and downstream effectors, like caspase-1 and IL-1β, can be measured as direct biomarkers and surrogate biomarkers by immunohistochemistry, qRT-PCR in tumor tissues of biofluids." (PMID 41560727, 2025). "The findings demonstrated high expression of AIM2 in tumor tissues and low expression of CASP1, NLRP 3, and NLRP1 in tumor tissues." (PMID 40026444, 2025). "As expected, caspase-1 expression increased as a consequence of the tumor cells’ contact with the GF + PTX and GFAP + PTX scaffolds compared with the normal cells and unenriched scaffolds, GF and GFAP (p < 0.01 and p < 0.001, respectively)." (PMID 39940603, 2025). "To ensure that deterred tumor development was linked to pyroptosis led by the reduction of HOXC8, we performed immunohistochemistry to analyze the abundance of HOXC8, caspase-1, Ki67 and cleaved caspase-3 in tumors excised from Chol-NC and Chol-siHOXC8 groups." (PMID 40701951, 2025). "The caspase-1 inhibitor VX-765 has shown anti-tumor effects through the inhibition of pyroptosis and reduction in IL-1β secretion in non-small cell lung cancer (NSCLC) models." (PMID 40141358, 2025). "In accordance with the NLRP3 expression variation, the GFAP + PTX scaffold promoted a significant increase in the caspase-1 expression in tumor cells compared with the GF + PTX scaffold (p < 0.05), strengthening the results obtained previously." (PMID 39940603, 2025). "Increased expression of Caspase-1 serves as a marker for heightened tumor aggression and poor prognoses." (PMID 40008397, 2025). "In CAR-T therapy, granzyme B cleaves GSDME in tumor cells, which triggers macrophage activation of caspase-1/GSDMD and leads to IL-1β/IL-6 release." (PMID 41291696, 2025). "Caspase-1 participates in the execution phase of apoptosis and has been found to potentiate the pro-tumor effect of TAMs." (PMID 40759978, 2025). "The question arises as to how the SNRPE targeting induces pyroptosis through the cleavage of caspase-1/GSDMD in tumor cells." (PMID 40386046, 2025). "Its pyroptotic activity has been observed in HCC and other tumor cells, primarily mediated by caspase-1 activation." (PMID 39316325, 2025). "Elevated tumoral caspase-1 is associated with a distinct TIME characterized by increased pro-tumoral TAMs and CD8+ T cell exclusion from tumor nests." (PMID 39353903, 2024). "CDKN1C inhibits proliferation and CASP1 mediates pyroptosis—a form of cell death triggered by proinflammatory signaling, thus representing tumor suppressor genes." (PMID 38474011, 2024). "The functional importance of caspase-1 in CD8+ cell exclusion from the tumor core implied by our survey of human tumors, was confirmed using KBP allografts." (PMID 39353903, 2024). "Simvastatin possesses anti-tumor effects by downregulating ROS production and inducing downstream caspase-1-dependent pyroptosis." (PMID 39011036, 2024).
tumor (continued). "On the other hand, the inhibition of NLRP3 inflammasome using MCC950 reduced LPS, ATP, PTX-mediated caspase-1 and IL-1β release, both in normal cells (p < 0.01 and p < 0.001, respectively) and tumor cells (p < 0.001 and p < 0.0001, respectively)." (PMID 39433537, 2024). "Their results revealed that the NLRP3 inflammasome exerted a tumour-promoting effect by activating caspase-1 in PCa." (PMID 38103146, 2024). "More recently, Alisol A, a marine herb with anti-tumor effects, was found to induce pyroptosis by increasing the levels of caspase-1, GSDMD, and GSDME in CRC cells, while reducing cancer cell migration and increasing the chemosensitivity of cisplatin." (PMID 39062587, 2024). "Caspase-1 positive cells and immune infiltrates were quantified in whole tumor, in tumor epithelial nests (CKpos) and in tumor stroma (CKneg)." (PMID 39353903, 2024). "Experiments in hepatocellular carcinoma tissues from patients have shown that IFI16 induces the formation of inflammasomes in tumor cells, promoting cell death, an effect that can be inhibited by a caspase-1 inhibitor." (PMID 38523155, 2024). "Along with the increase of NLRP3, ASC and IL-1β expression levels, an increasing caspase-1 expression profile was obtained for PTX-treated tumor cells compared untreated cells." (PMID 39433537, 2024). "For instance, sorafenib has been reported to induce pyroptosis in macrophages by targeting caspase-1-dependent inflammasomes, thereby activating cytotoxic natural killer (NK) cells and precipitating tumor cell death." (PMID 39117626, 2024). "In vivo, okanin reduced tumor growth and involved pyroptosis-related markers such as CASP1, GSDMC, GSDMD, and GSDME." (PMID 39335166, 2024). "Activated caspase-1 promotes proteolytic cleavage of pro-IL-1β, allowing IL-1β maturation, and tumor-associated macrophages recruitment to the TME and, therefore, tumor progression." (PMID 39625520, 2024). "This interaction underscores the potential role of BA in modulating NLRP3-caspase-1 signaling, thereby facilitating the release of inflammatory factors during tumor cell pyroptosis via the NF-κB pathway." (PMID 38169542, 2024). "Tissues were stained for pan-cytokeratin (panCK; tumor epithelium), caspase-1, CD3 (lymphocytes), CD8 (CTL), CD68+ (monocytes/macrophages), and CD163+ (M2-like, protumoral TAMs)." (PMID 39353903, 2024). "These genes included those related to P/DAMP signaling (e.g., Il6, Tlr1, Tlr4, Il1b, Il18), necroptotic tumor cell death (e.g., Casp1, Casp8, Il1b), and activation of the adaptive immune system (e.g., Cd80, Cd8a, Ccr5, Cxcl10)." (PMID 37213298, 2023). "The results demonstrated that the combination between miR-155-5p antagomir and cetuximab regulates GSMDE and CASP1 in order to stimulate the pyroptotic cell death and to decrease tumor growth." (PMID 36834660, 2023). "Studies have indicated that CASP1-induced pyroptosis combined with immune checkpoint inhibitors (ICIs) can enhance anti-tumor immunity in vitro and in vivo." (PMID 36834660, 2023). "Using Se-PC as a photosensitizer in tumors, pyroptosis was the primary type of tumor death by increasing the activity of Caspase-1 and Caspase-3 and reducing the activity of Caspase-8 and Bcl-2." (PMID 37994159, 2023). "While the effect of NLRP3 activation on tumor development is controversial, the inflammasome-dependent activation of caspase-1 is reported to have an antitumor effect." (PMID 37308559, 2023). "The results showed that the expression of CASP1 in patients with tumor diameter > 5 cm was lower than that in patients with tumor diameter ≤ 5 cm(P < 0.05)." (PMID 37194012, 2023). "The NLRP3 inflammasome has been observed to be activated in DCs during chemotherapy and enhanced the anthracycline-induced anti-tumor immune response by secreting caspase-1 and IL-1β." (PMID 37497237, 2023). "METTL3 reduces tumor cell death through the circCUX1/caspase 1 axis and confers radiation resistance to HPSCC." (PMID 37264402, 2023).
tumor (continued). "P2X7 receptor plays an important role in the NLRP3/caspase-1 cascade, which can promote tumor proliferation, migration and invasion." (PMID 37020871, 2023). "When tumor cells exist in an inflammatory microenvironment, Caspase-1 actively induces the programmed death of tumor cells." (PMID 37264402, 2023). "Recent studies have shown that the expression of NLRP3, AIM2 and caspase-1 was significantly increased in tumor specimens from melanoma patients who had been effectively treated with PD-1." (PMID 37497237, 2023). "This shows that in hypoxic HCC cells, histone H3 activates TLR9, induces caspase-1 activation and subsequently produces a variety of inflammatory mediators, which in turn promotes tumor proliferation and metastasis." (PMID 37082731, 2023). "Genes associated with a pro-inflammatory tumour microenvironment included TNF, IL6, IL18, NLRP3, IL1B and CASP1 which were also comparable between sporadic and NF2-SWN VS samples." (PMID 37680691, 2023). "GSDMD (p = 0.012) and IL-18 (p < 0.001) were highly expressed in tumor tissues, whereas NLRP3 (p < 0.001) and CASP1 (p = 0.001) expression was low in tumor tissues." (PMID 37864196, 2023). "For instance, PRGs, including NLRP3, Gasdermin D (GSDMD), Caspase 1 (CASP1), and Gasdermin E (GSDME), are highly associated with oncogenesis as well as tumor progression." (PMID 37149620, 2023). "Carcinoma cell embolus was found to significantly correlate with high NLRP3 expression in parenchymal cells of the tumor (x2=4.592, P=0.032), while the expression of caspase-1 was negatively correlated with tumor progression." (PMID 38031068, 2023). "Lymph node metastasis had significant difference with the CASP4 and GSDMD expression (P < 0.05); tumor volume had significant difference with CASP1 and CASP5 expression (P < 0.05)." (PMID 37194012, 2023). "Our study found that caspase-1 expressed in the parenchymal tumor cells was negatively correlated with tumor progression, for example, higher caspase-1 means smaller tumor size and lower invasive grade." (PMID 38031068, 2023). "Our study demonstrated the anti-tumor effect of nigericin on TNBCs by inducing concurrent Caspase-1/GSDMD-dependent pyroptosis and Caspase-3-dependent apoptosis." (PMID 37370831, 2023). "Caspase-1, also known as interleukin-1β convertase, activates IL-1β and IL-18 and releases them into the extracellular environment to regulate the tumor microenvironment." (PMID 37264402, 2023). "The increased NLRP3 and IL1B transcripts correlated with increased biochemical caspase-1 activity in the tumor infiltrating myeloid cells compared to those isolated from PBMC from cancer patients." (PMID 36439171, 2022). "GSDMD is activated by caspase-1 to execute pyroptosis, and others suggested that GSDMD is associated with tumor growth." (PMID 36439171, 2022). "qRT-PCR assay showed that the expression of IL1B (the downstream inflammatory factor of caspase-1) in tumor tissue was significantly higher than that in normal tissue." (PMID 36213831, 2022). "The analysis demonstrated that in comparison with normal brain tissues, 20 pyroptosis-related genes were upregulated in the tumor (e.g. CASP1 and CASP3), and 11 pyroptosis-related genes were significantly downregulated in the tumor (e.g. GSDMB and NLRP1)." (PMID 35274175, 2022). "Our previous reports demonstrated a role for caspase-1 in monocytic MDSCs as a tumor growth mediator in a T cell-independent manner to warrant IL-1β blockade in cancer therapeutics." (PMID 36439171, 2022). "In HPV-infected cells, the inflammasome AIM2 acts as a tumor suppressor by activating caspase-1 to promote pyroptosis of tumor cells." (PMID 35883480, 2022). "Sorafenib was demonstrated that acts through direct immune modulation involving caspase-1-related MΦ pyroptosis and the following release of inflammasome-cytokine enhanced the cytotoxicity of NK cytotoxicity for the efficient tumor cell killing." (PMID 36119049, 2022).